PIK3CA (phosphatidylinositol-4,5-bisphosphate 3-kinase catalytic subunit alpha)
Diseases named in the same sentence as PIK3CA in open-access papers (continued):
Sharing a sentence is not in itself a finding about the gene and the disease.
cancer (continued). "PIK3CA gain-of-function mutations are one of the common genetic aberrations in human malignancies, which makes PI3K an attractive target for cancer therapy." (PMID 31889900, 2019). "PIK3CA enhances cancer cell proliferation, migration, cancer invasion, and interacts with growth factor-stimulated MAPK signaling." (PMID 31766556, 2019). "A few FDA approved serum BC markers worth mentioning are the Carcinoma Antigen 15-3 (CA 15-3), Carcinoma Antigen 27-29 (CA 27-29) and PIK3CA." (PMID 31500225, 2019). "Mutations in other conventional drivers (APC, KRAS, PIK3CA, ARID1A) were usually clonal within a carcinoma." (PMID 29991641, 2019). "A mutation in PIK3CA stimulates the AKT (protein kinase B) pathway and promotes cell growth in various cancers, possibly through increased expression of fatty acid synthetase (FASN)." (PMID 30071442, 2018). "The profiling of cancer mutation genes has identified significant differences in APC, ARIDIA, KMT2A, PIK3CA, and PTEN genes between GC patients of Asian and Caucasian." (PMID 29866191, 2018). "Crosstalk activation of the PI3K pathway via signalling through KRAS as well as mutations in PIK3CA and PTEN that occur in 17% and 21% of BRAF mutant cancers, respectively, can render cancer cells resistant to MAPK inhibition." (PMID 30598662, 2018). "PIK3R3 (p55γ subunit) is a regulatory subunit forming heterodimers with class IA p110α catalytic subunit (PIK3CA), the most studied catalytic subunit in cancer." (PMID 29682174, 2018). "Mutation of the PIK3CA gene, which encodes the catalytic subunit α (p110α), one of the class I PI3K isoforms, is found in several cancers." (PMID 30363988, 2018). "Mutational profiling for >150 mutations across commonly mutated cancer genes including RAS, PIK3CA, BRAF, and PTEN as well as treatment data, including receipt of a biologic agent, were collected." (PMID 29771009, 2018). "The PI3K/AKT pathway is an important therapeutic target because its components, including PIK3CA, are frequently activated in cancer cells; indeed, several PI3K pathway inhibitors are currently in clinical trials." (PMID 29484141, 2018). "The presence of PIK3CA copy number gain in a limited number of PeIN suggests it to be an early event in penile carcinogenesis, which becomes enriched with cancer progression." (PMID 29902261, 2018). "In contrast, rDriver, which examines the expression levels of all the genes (including those in distant pathways), indicated PIK3CA as a driver gene that impacts cell cycle, amino acid metabolism, cancer pathway, etc." (PMID 29738578, 2018). "Additional biomarkers currently being studied for application in cancer treatment include the PIK3CA, HER2, BRAF, ROS, RET, NRAS, MET, and MEK1." (PMID 29721208, 2018). "Remarkably, PIK3CA E542K (TCA > TTA) and E545K (TCA > TTA) were associated with these signatures across five cancer types, accounting for 82% (9/11) of all APOBEC associations." (PMID 29748584, 2018).
cancer (continued). "There were 21 variants that had allele frequencies > 0.02 in the sample of 621 cancer patients, 17 of which were common germline SNPs and 4 of which were common somatic driver mutations (2 in KRAS and 2 in PIK3CA)." (PMID 29721196, 2018). "Cancer-related protein PIK3CA was identified as the putative target for a series of imidazolium salt derivatives by the PharmMapper platform and PPI network." (PMID 29562629, 2018). "PIK3CA, the catalytic domain of PI3K, is an oncogene that is frequently mutated or amplified in cancer." (PMID 30012111, 2018). "It must be noted, however, that sensitivity to drug response in cell lines does not necessarily translate over to clinical efficacy, and RAS- and PIK3CA-mutant cancers continue to be controversial." (PMID 30053901, 2018). "And the other endpoints concerning patients with PIK3CA–mutant cancer were too sparsely reported for a meta-analysis to be feasible." (PMID 30235292, 2018). "In the first instance, the region of interest contains a known oncogene, PIK3CA (Gain 6), which has a well-established role in cancer development." (PMID 29371888, 2018). "For instance, PIK3CA E545K was predominantly clonal with high cancer cell fractions in LUAD, BRCA, BLCA, LUSC and HNSC, but was often sub-clonal in GBM and KIRC." (PMID 29738578, 2018). "Our objective was to evaluate relationships between mTOR-pathway activity and functional mutations in the upstream genes PIK3CA and PTEN in solid-tumor biopsies from a broad selection of cancer types." (PMID 29137436, 2017). "Taken together, these results indicate that BKM120 induces the translocation of FOXO3a from the cytoplasm to the nucleus depending on PIK3CA-mutant cancer cell type, resulting in the activation of FOXO3a and subsequent autophagy induction." (PMID 28036259, 2017). "When applied on 40 ng of DNA from fresh HCT116 cells, eight variants were detected, including KRAS (p.G13D), PIK3CA (p.H1047R), and CTNNB1 (p.S45del), with all of them being reported in ATCC or in COSMIC (Catalog of Somatic Mutations In Cancer)." (PMID 29263843, 2017). "As shown in our study, pharmacologic or RNA interference-based inhibition of autophagy enhances the efficacy of BKM120 depending on PIK3CA-mutant cancer cell type." (PMID 28036259, 2017). "Mutant PIK3CA promotes the proliferation and invasion of human cancer cells and confers resistance against HER2-targeted therapy for breast cancer, thus warranting further investigation as a potential therapeutic target." (PMID 29207615, 2017). "In that study of 1,656 patients with advanced, refractory cancers tested for PIK3CA or PTEN abnormalities, PIK3CA mutations were found in 9% of patients, and PTEN loss and/or mutation was found in 13% of patients." (PMID 28423515, 2017). "Several COSMIC cancer genes were found to have various mutations in multiple samples, including PTEN, PIK3CA, BRCA2, and ATM." (PMID 28852190, 2017). "There was significant overlap; 8/14 genes involved in OGID were somatically mutated in a diverse range of cancers (NSD1, EZH2, DNMT3A, PTEN, CHD8, HIST1H1E, MTOR, PIK3CA; p = 1.7 × 10−14)." (PMID 28475857, 2017). "A total of 409 genes from the Ampliseq Comprehensive Cancer Panel (Ion Torrent, Thermo Fisher) were analysed by next generation sequencing and mutations in 10 genes, including ARID1A, CTNNB1, PIK3CA and PTEN were identified and confirmed by Sanger sequencing." (PMID 28103826, 2017). "MSH3, MSH6, APC and PIK3CA genes seem to play a bigger role in the path to cancer in this population." (PMID 28002797, 2017).
cancer (continued). "Taken together, these findings suggest that the release of FOXO3a from 14-3-3 is required for the induction of autophagy by BKM120 in PIK3CA-mutant cancer cells." (PMID 28036259, 2017). "In cancer cell lines, p110α inhibition reduces cell viability by inducing cell death in PIK3CA mutant cells while p110β inhibition delayed proliferation in PTEN-deficient cells, but not in WT cells." (PMID 28002804, 2017). "Cancer cells carrying PIK3CA mutations are more sensitive to BYL719, while tumors bearing PIK3CA amplifications or PTEN mutations only respond moderately." (PMID 28592260, 2017). "Mutant PIK3CA activates Akt pathways, which in turn promote the growth and invasion of cancer cells." (PMID 29207615, 2017). "The first step to developing such a therapy is to identify genes that are essential for cancer cells to survive when they are exposed to the PIK3CA-inhibiting drug." (PMID 28561737, 2017). "PIK3CA mutations can lead to resistance to MET inhibition, supporting future clinical evaluation of combinations of PI3K and MET inhibitors in common scenarios of malignant neoplasms featuring aberrant MET expression and PIK3CA mutations." (PMID 28532501, 2017). "The amplification rate for PIK3CA, a known oncogene in many types of human cancer, was 38.3% (36/94) and only two samples with PIK3CA amplification displayed concurrent mutations." (PMID 28548104, 2017). "Alterations in PI3K signaling (especially PIK3CA) were suggested for therapeutic targeting in carcinomas, although the pathway was altered in a subset of tumors (11.7%)." (PMID 28586388, 2017). "Some important cancer genes, such as PIK3CA, BRCA1, BRCA2, and ERBB2, show a mixture of amplifications and deletions." (PMID 27556158, 2016). "The role of PI3Kβ in cancer is less understood; PIK3CB mutations in cancer appear at lower frequency than those of PIK3CA, but enhanced PI3Kβ expression is sufficient to induce transformation." (PMID 27863432, 2016). "GDC-0941 is an oral class I pan-PI3K inhibitor with activity in the nanomolar range against a wide range of cancer cell lines that has preclinical activity in models harbouring pathway alterations in PIK3CA, PTEN, or HER2." (PMID 27489350, 2016). "Our study demonstrated that the M and C class changes in an individual cancer driver gene, such as PIK3CA or GATA3, are correlated with opposite histologic changes." (PMID 27283966, 2016). "Other frequently mutated EAC driver genes included NOTCH1 (N=8 cancers), ARID1A (N=7), CNTNAP5 (N=3), PIK3CA (N=3) and SMARCA4 (N=3)." (PMID 27045317, 2016).
cancer (continued). "PIK3CA, which encodes the phosphoinositide 3-kinase (PI3K) subunit p110α, is frequently mutated in many cancers, including GBC." (PMID 27317099, 2016). "PIK3CD, instead, belongs to the same class I of PIK3CA/B/G and has been found amplified or overexpressed in cancer." (PMID 26860319, 2016). "Other mutations (such as non-T790M EGFR mutations D761Y, L747S and T854A, amplification of c-Met, loss of PTEN, PIK3CA mutations and BIM BH3 deletion) have been reported to result in the resistance to EGFR TKIs in some cancers." (PMID 26909593, 2016). "Mutations in the phosphatidylinositol-4,5-bisphosphate 3-kinase, catalytic subunit alpha (PIK3CA) gene, which encodes the p110 catalytic subunit of PI3K, have been found in several types of carcinoma." (PMID 27388016, 2016). "One important question is the possible effect of PIK3CA status on cancer outcome and treatment efficacy." (PMID 26452060, 2015). "MSI cases are generally characterized by accumulation of mutations in PIK3CA, ERBB3, ERBB2, and EGFR; along with mutations present in ‘hotspot’ sites that have been identified in other cancers." (PMID 26267324, 2015). "Recent reports also reveal that combination of aspirin with conventional chemotherapeutic agents, such as sorafenib and TRAIL, can exhibit enhanced anti-cancer effects both in PIK3CA mutant and PIK3CA wild-type cancer cell lines 2,7." (PMID 25388762, 2015). "The PentaPanel platform assesses single nucleotide polymorphisms in 56 hotspots of the 5 most clinically relevant cancer genes, KRAS, NRAS, BRAF, EGFR and PIK3CA for a total of 221 detectable mutations." (PMID 26435479, 2015). "Mutations in the catalytic subunit of phosphoinositide 3-kinase (PIK3CA) and other PI3K-AKT pathway components have been associated with cancer and a wide spectrum of brain and body overgrowth." (PMID 26633882, 2015). "In cancer, this pathway can be constitutively activated, most commonly by loss of PTEN or an activating mutation in the PIK3CA gene that encodes the p110α catalytic subunit of PI3K." (PMID 26402468, 2015). "While mutations in KRAS, BRAF, PIK3CA, and EGFR were found in cancer types expected, there were also several instances of actionable mutations identified in diseases for which these mutations have not been well characterized." (PMID 26015395, 2015). "Among the cancer cell lines used in this study, both CNE2-S18 and CNE1 cell lines were previously confirmed to have hyper-activated PI3K/AKT signaling due to the PIK3CA and HRAS mutation, respectively." (PMID 25749514, 2015). "PIK3CA is amplified in various cancers and up to 70% of the CSCCs are known to harbor PIK3CA amplification." (PMID 25738363, 2015).
cancer (continued). "These potential alternative driver alterations were found to affect known cancer genes, including amplification of PIK3CA or MYC, and likely driver genes mapping to the 8p11-p12 amplicon, including ZNF703, RAB11FIP1, LSM1, PPAPDC1B, WHSC1L1 and FGFR1." (PMID 25994018, 2015). "The relation of PIK3CA to these pathways, as well as its pivotal role in human cancers, is a consequence of it being a key player in activation of signaling cascades involved in cell growth, survival, proliferation, motility and morphology." (PMID 25965968, 2015). "BRP negatively regulated the expression of numerous genes involved in the development of several types of cancer such as: fos, elk1, Pik3ca, Prkca." (PMID 26660901, 2015). "Recently, mutations in PIK3CA, which encodes the catalytic subunit of PI3K, were identified in various human cancers." (PMID 26137586, 2015). "There is also evidence of PIK3CA amplification and overexpression in different cancers, as well as numerous other oncogenic abnormalities, including frequent mutation, deletion and loss of expression of the tumour suppressor gene PTEN." (PMID 26117819, 2015). "In only 1 of 14 cases was a PIK3CA mutation present in both the patient match CCL and the concurrent carcinoma." (PMID 25918554, 2015). "It is frequently deregulated in a majority of human cancers through receptor tyrosine kinase activation or amplification such as loss of PTEN (phosphatase and tensin homolog), activating mutations of PIK3CA, or other downstream effectors of PI3K/Akt signaling." (PMID 25389442, 2014). "The second most popular gene was PIK3CA, which was found in six cancers (BRCA, COAD, READ, GBM, LUSC, and UCEC), although it was only identified by the MSEA-clust method." (PMID 25348067, 2014). "For example, in phase 1 clinical trials, patients with PIK3CA-aberrant cancer had a higher clinical response rate to treatment with PI3K/AKT/mTOR inhibitors than patients who lacked these aberrations." (PMID 25593991, 2014). "We used two different p110α inhibitors, MLN1117 and A66, at concentrations that suppress signaling and growth of PIK3CA mutant cancer cells." (PMID 24915189, 2014). "Mutations and, to a lesser extent, increased copy numbers in another prevalent oncogene, PIK3CA, have been characterized in diverse cancers." (PMID 25204415, 2014). "PIK3CA mutations are tightly linked to the luminal subtypes whereas MYC amplification is common in both basal and luminal cancers." (PMID 25091696, 2014). "Oncogenic PIK3CA is mainly activated through gene amplification and “gain of function” single-nucleotide substitution in human cancers." (PMID 24511546, 2014). "Based on cBio cancer genomics portal, H4 cell line has PTEN homozygous deletion and EGFR amplification; NCI-H1975 and CAOV-3 both have a PIK3CA mutation and an EGFR mutation." (PMID 25361177, 2014). "When PIK3CA and AKT1 are downstream effectors of RAS, both HRAS and RAC1 are RAS superfamily of small GTPases that cause cancer growth, invasion, and metastasis." (PMID 25356910, 2014). "The function of mutant PIK3CA protein compared with the wild type has beencharacterized in both human cancer cell lines and human mammary epithelial cells,mainly using gene targeting approaches." (PMID 25192370, 2014). "We did observe higher proliferation rates in exon 20 PIK3CA mutant cancers, consistent with previous reports showing differences in prognostic value between exon 9 and exon 20 mutations, though sometimes in opposing directions." (PMID 24520381, 2014).